PGR (progesterone receptor)
Diseases named in the same sentence as PGR in open-access papers (continued):
Sharing a sentence is not in itself a finding about the gene and the disease.
breast cancer (continued). "Triple-negative breast cancer (TNBC) is an aggressive histological subtype of breast cancer characterized by the lack of estrogen receptor (ER), progesterone receptor (PR), and lack of amplification/overexpression of human epidermal growth factor receptor 2 (HER2)." (PMID 36531071, 2022). "Based on receptor type, BC was categorized into four groups: HER2+, ER-(progesterone receptor) PR-HER2-, A/B (ER and/or progesterone receptor PR positive and triple-negative breast cancer (TNBC)." (PMID 36119495, 2022). "HER2+ breast cancer (BC) is an aggressive subtype representing a genetically and biologically heterogeneous group of tumors resulting in variable prognosis and treatment response to HER2-targeted therapies according to estrogen (ER) and progesterone receptor (PR) expression." (PMID 35052843, 2022). "Triple negative breast cancer (TNBC) represents the clinical subtype of breast cancer that is negative for immunohistochemistry (IHC)-based assessment of estrogen receptor (ER), progesterone receptor (PR), and human epidermal growth factor receptor 2 (HER2) amplification." (PMID 34381029, 2021). "Triple-negative breast cancer (TNBC) is a subtype of breast cancer that accounts for about 15–20% of all breast cancers and is defined by tumors lacking estrogen receptor expression, progesterone receptor expression, and human epidermal growth factor receptor-2 (HER2) overexpression/amplification." (PMID 33974630, 2021). "To further determine the clinical pertinence of NLGN2 in breast cancer, we assessed its prognostic performance in different intrinsic subtypes with or without the estrogen receptor (ER), progesterone receptor (PR) and Erb-B2 receptor tyrosine kinase 2 (HER2) expression." (PMID 34804909, 2021). "Four main subtypes of breast cancer have been identified, corresponding to triple-negative breast cancers (TNBCs, negative for estrogen receptor (ER), progesterone receptor (PR) and Her2), Her2-positive breast cancers and two types of luminal breast cancers (luminal A and B, positive for ER)." (PMID 34066060, 2021). "Triple-negative breast cancer (TNBC) represents 15% of all breast cancer types, and is defined by the lack of significant estrogen receptor (ER) and progesterone receptor (PR) expression, and the absence of human epidermal receptor 2 (HER2) overexpression/amplification." (PMID 34885167, 2021). "The first trial was an open-label, two-arm, phase III, randomized study to evaluate efficacy and safety of the 12-month CM maintenance regimen versus no CM after standard adjuvant chemotherapy for ER and PgR negative (<10 %) with any HER2 status of early breast cancer." (PMID 34407499, 2021). "Triple-negative breast cancer (TNBC) is the most aggressive subtype of breast cancer, which is characterized by the absence of estrogen receptor (ER) and progesterone receptor (PR) expression and the absence of human epidermal growth factor receptor 2 (HER2) expression/amplification." (PMID 34778045, 2021). "Triple negative breast cancer (TNBC) accounts for 12–17% (depending on immunohistochemical cut-offs used) of all breast cancer patients and are defined by the lack of expression of estrogen receptor (ER), progesterone receptor (PR), and human epidermal growth factor receptor 2 (HER2)." (PMID 33542435, 2021). "Furthermore, NGAL level was elevated in the breast cancer patients who were negative progesterone receptor status, had a histologic grade ≥ 2, clinical stage III, and pathologic stage T2+T3+T4." (PMID 34104101, 2021). "Notably, a significant correlation between LCN2 expression with other markers including ER− negative or progesterone receptor (PR)-negative status has been reported in breast cancer." (PMID 34072157, 2021).
breast cancer (continued). "Present in pre-malignant mammary lesions and tumors, CA is more prevalent in triple-negative (estrogen and progesterone receptor-negative and non-amplified for Her2, or ER-PR-Her2-) breast cancer subtype and correlates with stage, grade, and poor survival of breast cancer patients." (PMID 33907253, 2021). "According to the expression of hormone receptors, breast cancer can be divided into four subtypes: Luminal A breast cancer is hormone-receptor positive (estrogen-receptor and/or progesterone-receptor positive), HER2 negative, and has low levels of the protein Ki-67." (PMID 34660251, 2021). "However, about 12–20% of all breast cancers are negative for ER, progesterone receptor (PgR), and Her2, comprising the triple negative breast cancer (TNBC) group." (PMID 34685748, 2021). "As breast cancer subtypes, ER negative (p < 0.001), PgR negative (p < 0.001), HER2 positive (p = 0.002), and high Ki67 (p = 0.005) were significantly more likely to achieve pCR, so HER2BC (p < 0.001) and TNBC (p = 0.031) were significantly more likely to have pCR." (PMID 34670511, 2021). "Triple-negative breast cancer (TNBC) is a subtype of breast cancer that comprises various disease entities, all of which share a set of common features: a lack of expression of the estrogen receptor, progesterone receptor, and human epidermal growth factor receptor 2, respectively." (PMID 34685748, 2021). "No miRNAs were found to be differentially expressed between the various molecular subtypes of breast cancer (estrogen receptor-positive, progesterone receptor-positive, and HER2 overexpressed) nor did any miRNA perform better as a biomarker for a certain molecular subtype." (PMID 33925125, 2021). "Breast cancer is a complex and highly heterogeneous disease which is typically classified in molecular subtypes according to the expression of specific factors such as estrogen receptor (ESR1), progesterone receptor (PGR) and human epidermal growth factor receptor 2 (HER2)." (PMID 34809697, 2021). "Breast cancer is stratified into luminal, human epidermal receptor 2 (HER2)-enriched, and triple-negative breast cancer (TNBC) subtypes, according to the presence of distinct molecular markers, including the estrogen receptor (ER), progesterone receptor (PR), and HER2." (PMID 34683150, 2021). "Triple-negative breast cancer (TNBC), which constitutes approximately 12–17% of breast cancer cases, is a heterogeneous subtype characterized by the absence of estrogen receptor (ER), progesterone receptor (PR), and human epidermal growth factor receptor 2 (HER2)." (PMID 33747911, 2021). "Breast cancer can be divided into the molecular types—luminal A, luminal B, ERBB2+, and triple negative breast cancer (TNBC)—based on different expression profiles of the estrogen receptor (ER), progesterone receptor (PR), and human epidermal growth factor receptor 2 (HER2)." (PMID 34563270, 2021). "Estrogen receptor (ER), progesterone receptor (PR), and human epidermal growth factor receptor 2 (HER2) define the prognosis, identify tumors for targeted therapy, and remain the sole established single-molecule biomarkers defining the minimum breast cancer pathology data set." (PMID 34829293, 2021). "Systemic therapy for breast cancer is determined from the presence or absence of estrogen receptor (ER), progesterone receptor (PR), and human epidermal growth factor receptor II (HER2) status as well as pathological factors such as nuclear grade and Ki-67 expression." (PMID 34387660, 2021).
breast cancer (continued). "The use of oral progestin, despite requiring longer treatment time, is effective in relation to the gonadotropin-releasing hormone antagonist protocol and offers greater comfort at a lower cost in progesterone receptor negative breast cancer patients undergoing cancer fertility preservation." (PMID 34431852, 2021). "TNBC is an aggressive HER2-, estrogen, and progesterone receptor-negative mammary carcinoma." (PMID 34829808, 2021). "Triple-negative breast cancer (TNBC) accounts for 15–20% of all breast cancer cases and is a subtype of breast cancer characterized by the lack of oestrogen receptor (ER), progesterone receptor (PR) and ErbB-2/human epidermal growth factor receptor 2 (HER-2) expression." (PMID 32661222, 2020). "The immunohistochemical profile showed that 50% of women with breast cancer had positive estrogen receptor (ER) and 50% had negative estrogen receptor, and there was a predominance of 56.7% for positive progesterone receptor (PR) and 80% negative for human epidermal growth factor receptor 2 (HER2)." (PMID 32405338, 2020). "A phase II clinical trial evaluating bicalutamide, a first-generation AR antagonist, in AR-positive/ERα-negative/PgR-negative advanced breast cancers, showed a clinical benefit rate of 19% at 6 months and a median progression-free survival duration of 12 weeks." (PMID 31952272, 2020). "In addition, we report here, on the basis of phenotype, that GI and GII inhibit the migration of triple-negative (ER-, PgR-, HER2NEU-) MDA-MB-231 breast cancer cells, and that they inhibit the expression of genes which code for important regulators of cell migration and invasion in cancer tissues." (PMID 32085612, 2020). "Triple-negative breast cancer (TNBC), accounting for 15–20% of breast cancers, does not benefit from endocrine therapy or classic targeted therapy due to the absence of estrogen receptor (ER), progesterone receptor (PR), and the human epidermal growth factor receptor (HER-2) gene amplification." (PMID 32922222, 2020). "Crosstalk between progesterone receptor, stimulated by progesterone, is expressed by the interaction between the progesterone receptor and RANKL, results in RANKL to RANK binding and activates cell proliferation and subsequently unlimited expansion of the breast cancer cells." (PMID 32183159, 2020). "As the vast majority of ER(−)/PgR(+) breast cancer express low levels of PgR, it may suggest that in some cases miR-495-3p contributes to a lack of ER expression with retained low PgR expression." (PMID 32825530, 2020). "More importantly, as cGMP signaling is a common signaling pathway in all types of breast cancer and largely independent of the estrogen receptor, progesterone receptor or HER-2 receptor, targeting this pathway is a promising and novel approach to improve triple-negative breast cancer survival rates." (PMID 33186350, 2020). "Interestingly, we found that ts-34 downregulated genes were enriched for breast cancer (general schema) pathway, where absent expression of PGR was correlated with poor survival." (PMID 32785169, 2020). "There are differences between two subtypes of breast cancers: triple-negative canine mammary cancer cell lines are negative for estrogen receptor (ER), progesterone receptor (PR), and HER-2, while HER-2 enriched cell lines are generally HER-2–positive and lymph node–positive." (PMID 33263014, 2020). "Recent studies have revealed that intrinsic subtypes of breast cancers characterized by ER-negative, PgR-negative, and HER2-negative expression (i.e., triple-negative breast cancer [TNBC]), or by ER-negative, PgR-negative, and HER2-positive expression have a poor prognosis." (PMID 31372841, 2020). "Owing to the complexity of breast cancer and the essential role of both HER2 and hormone receptors (ER and PgR) in its biology, we were interested in evaluating the differences in miRNA profiles between the four ER/PgR/HER2 phenotypes of single hormone receptor-positive primary breast tumors." (PMID 32825530, 2020).
breast cancer (continued). "Triple-negative breast cancer (TNBC) is a subtype of breast cancer in which the estrogen receptor and progesterone receptor are not expressed, and human epidermal growth factor receptor 2 is not amplified or overexpressed either, which make the clinical diagnosis and treatment very challenging." (PMID 34138297, 2020). "Additionally, there are few effective adjuvant therapy options for this group and for the so-called triple-negative (TNP) breast cancers that lack expression of ER, progesterone receptor (PR) and human epidermal growth factor receptor 2 (HER2)." (PMID 32370743, 2020). "Triple-negative breast cancer (TNBC) constitutes around 15% of all breast cancer cases and is characterized by tumors that do not express estrogen receptor (ER), progesterone receptor (PR), and do not overexpress human epidermal growth factor receptor 2 (HER2)." (PMID 33282730, 2020). "Triple-negative breast cancer (TNBC) is a highly heterogeneous disease, representing the most aggressive breast cancer (BC) subtype with limited treatment options due to a lack of estrogen receptor alpha (ERα), progesterone receptor (PR), and Erb-B2 receptor tyrosine kinase 2 (HER2/neu) expression." (PMID 32260128, 2020). "Subgroup analyses show that in nontriple negative breast cancer (non-TNBC) patients, the high SMC4 mRNA expression, older age (>65), negative progesterone receptor, and advanced stages (III-IV) were independent risk factors (HR = 3.293, 95% CI 1.257-8.625, P = 0.015)." (PMID 31871499, 2019). "This study involved 81 node-negative, estrogen receptor-positive and/or progesterone receptor-positive and human epidermal growth factor receptor 2-negative operable breast cancer patients who underwent radical surgical resection and received adjuvant endocrine therapy." (PMID 30646864, 2019). "Additionally, we further explored the relative gene expression of other important hormonal receptors in breast cancer, such as estrogen receptor beta (ESR2), progesterone receptor (PGR) and androgen receptor (AR), concomitantly with estrogen receptor alpha (ESR1)." (PMID 31817155, 2019). "The heterogenicity of breast cancer (BC) is determined by the status of human epidermal growth factor receptor 2 (HER2/neu), estrogen receptor (ER), and progesterone receptor (PR)." (PMID 31897358, 2019). "Also, the relationship between OCs use and specific subtypes of breast cancer [Estrogen Receptor-Positive (ER+), Estrogen Receptor-Negative (ER-), Human Epidermal growth factor Receptor 2-Positive (HER2+), Progesterone Receptor-Positive (PR+)] should be evaluated." (PMID 31159800, 2019). "Triple Negative Breast Cancer (TNBC) is a highly aggressive subtype, accounting for 10–20% of all diagnosed breast cancers, with no targeted therapy available due to the lack of oestrogen and progesterone receptor expression and the absence of HER2 amplification." (PMID 31003528, 2019). "Triple negative breast cancer is an aggressive subtype of breast cancer characterized by lack of expression of estrogen receptor (ER), progesterone receptor (PR), and human epidermal growth factor receptor (HER2) and accounts for more than 10% of all breast cancers." (PMID 31882647, 2019). "Hence, this study compared the original PEPI to a modified p-PgR status alone and a modified PEPI including the PgR status (PEPI-P) as a prognostic factor for NAE in postmenopausal patients with ER-positive and HER2-negative breast cancer." (PMID 30080878, 2018). "It is worth noting that all of these genes except PGR (P<0.05) and CCND1 (P<0.01) which were down-regulated, were up-regulated in ER+ MCF-7 cells by 4-OH-TAM, confirming their pathophysiological relevance and possible involvement in mediating the anti-breast cancer effects of TAM." (PMID 29416786, 2018). "In addition, different lipoprotein subfractions vary by progesterone receptor expression, suggesting the influence of HDL-cholesterol on breast cancer prognosis may differ by breast cancer phenotype." (PMID 29902993, 2018).
breast cancer (continued). "In contrast, basal-like is one of the most aggressive types of breast cancer lacking estrogen receptor (ER), progesterone receptor (PR) and HER2, and possessing a high expression of epithelial-to-mesenchymal transition markers as well as enrichment in stem cell-like features." (PMID 30275391, 2018). "Within the subtypes of breast cancer, those identified as triple negative for expression of estrogen receptor α (ESR1), progesterone receptor (PR) and human epidermal growth factor 2 (HER2), account for 10–20% of breast cancers, yet result in 30% of global breast cancer-associated deaths." (PMID 30373175, 2018). "When a breast cancer metastasis is suspected, the expression of hormonal receptors [estrogen receptors (ERs) and progesterone receptors (PgR)] must be investigated, although their expression is not specific as observed in ovarian, endometrial adenocarcinomas, and bronchopulmonary adenocarcinomas." (PMID 29881714, 2018). "The TAILORx prospective trial examining the use of Oncotype DX scores to stratify treatment in ER+ (and/or progesterone receptor-positive), HER2-, node-negative early advanced breast cancer has reported 5-year results on its low-risk patient cohort assigned to receive endocrine treatment alone." (PMID 29128896, 2018). "Furthermore, we cannot presently explain why rural patients in the estrogen receptor–negative, progesterone receptor–negative, adjuvant breast cancer cohort had worse survival." (PMID 30646114, 2018). "Standard breast cancer biomarkers on the other hand, such as estrogen receptor (ER), progesterone receptor (PR), HER2, and Ki67, are not affected by cold ischemic time of 1 h, which is the maximum of delay to fixation for breast cancer specimens recommended by ASCO/CAP guidelines." (PMID 30595971, 2018). "Breast cancer is a heterogeneous disease that is classified into three subtypes: luminal, human epidermal growth factor receptor 2 (HER2)-enriched, and basal-like based on the presence of ERα (coded by the ESR1 gene), progesterone receptor (coded by the PGR gene) and HER21." (PMID 30375428, 2018). "In multivariable regression, rural patients with adjuvant-stage estrogen receptor–negative and progesterone receptor–negative breast cancer had worse overall survival (hazard ratio, 1.27; 95% CI, 1.06-1.51; P = .008) and cancer-specific survival (hazard ratio, 1.26; 95% CI, 1.04-1.52; P = .02)." (PMID 30646114, 2018). "However, this study was not specific to breast cancer, and did not examine the impact of prognostic factors such as estrogen receptor (ER) or progesterone receptor (PR) status, HER2 status, disease stage, or menopausal status." (PMID 28057046, 2017). "Triple negative breast cancer is characterized by the absence of the estrogenreceptor (ER), the progesterone receptor (PR) and low to normal levels of HER2,a receptor tyrosine kinase encoded by the ERBB2 gene that isoften amplified or overexpressed in breast cancer." (PMID 28521512, 2017). "Similarly, 59 of 72 (81.9%) progesterone receptor (PR)-negative paraffin-embedded breast cancer tissues displayed moderate or strong nuclear NSUN2 staining, whereas 49 of 119 (41.2%) PR-positive tumor samples showed a decrease in NSUN2 staining (P=0.001)." (PMID 27447970, 2017). "The regulation of the progesterone receptor in breast cancer has not been thoroughly studied." (PMID 28404930, 2017). "These authors have concluded that the lack of PgR expression might be an important determinant of tumor biology in Luminal types of breast cancers." (PMID 28356061, 2017). "In another report of 327 surgically removed ER positive and HER2 not-overexpressed breast cancers, only among postmenopausal patients it was reported that high Ki-67 value and low PgR expression (<20%) were significant independent factors for worse distant relapse-free survival." (PMID 28356061, 2017).